TNF (tumor necrosis factor)
Diseases named in the same sentence as TNF in open-access papers (continued):
Sharing a sentence is not in itself a finding about the gene and the disease.
infection (continued). "Increased local levels of several important proinflammatory cytokines, including TNFα, MIP-1α, IL-12 and IL-10, were associated with a decreased likelihood of elimination of the virus in women with established long-term infection." (PMID 25663851, 2015). "In vitro infection further increased the generation of NO2−, and IL-4 alleviated both the NO2− generation-induced by the bacteria alone (p < 0.01) and by the combined actions of infection, IFNγ and TNFα (p < 0.01)." (PMID 26481427, 2015). "The pro-inflammatory genes TNF-α and IL-1β are induced by the activation of NF-κB following LPS-induced infection." (PMID 26572495, 2015). "In patients with AS, there was a very clear temporal relationship between the initiationof TNFα blockers and the emergence of active infection, stressing that the mechanism ofLTBI reactivation was the most involved in these cases." (PMID 26560983, 2015). "In 1993, Leviton proposed that infection-induced upregulation of tumor necrosis factor alpha (TNF-α) can produce brain injury." (PMID 26407958, 2015). "Infection-associated induction of pro-inflammatory cytokines such as IFN-γ, TNF and IL-1β poses a double-edged sword." (PMID 26260055, 2015). "In intestine, the expression level of TNF-α after infection was significantly down-regulated at 3 h, up-regulated at 6 h, and down-regulated during the period from 12 to 72 h." (PMID 25988382, 2015). "Macrophages from MGL1−/− mice obtained during the early phase of infection with T. crassiceps (2 wks) produced lower levels of IL-12 and TNF-α compared with those from MGL1+/+ mice." (PMID 25664320, 2015). "A significant increase of IL-6 and TNF-α were also observed at 4 or 8 h following infection with D39 or TIGR4." (PMID 26683708, 2015). "After infection with the three virus strains, TNF-α levels of mice in all groups were only slightly higher than those of the PBS group at 2 dpi and increased at 4 and 6 dpi." (PMID 25888728, 2015). "To elucidate the role of the cytokine environment versus the direct actions of C. rodentium in vivo, we studied IFNγ−/− mice, as IFNγ increased early in infection, concomitantly with the mitochondrial dysfunction (in contrast to TNFα)." (PMID 26481427, 2015). "We next examined the role of TNF to control cerebral inflammation by analysis of sectioned brain tissue for induced pathology in M. tuberculosis-infected mice at 3 weeks post-infection." (PMID 26112704, 2015). "As expected, TNFα, IL6 and IFNγ cytokines were enhanced by the infection, which have been associated with the progression of hepatic and cardiac injury." (PMID 25668433, 2015). "Our results show that MyD88 proinflammatory cytokines (TNF-α and IL-1β) and transcriptional and translational products, increase after infection." (PMID 26021751, 2015). "P65 NF-κB knockdown reduced the ability of HCV to induce the expression of TNF-α at both 2 hours and 24 hours post-infection." (PMID 26023919, 2015). "After infection with tdTomato-expressing M. marinum, we found that the TNF reporter was active in cells within and directly surrounding the bacteria-laden core of the granuloma." (PMID 26449262, 2015). "An enhanced binding of p65 NF-κB to the TNF-α promoter was observed in HCV-infected cells at 2 hours post-infection." (PMID 26023919, 2015). "Consistent with this, MIF-deficient mice were more susceptible to infection with Salmonella typhimurium, producing lower levels of IL-12, IFN-γ, and TNF-α." (PMID 26617609, 2015). "Our data show a significant increase in the frequency of TNFα-producing macrophages upon infection with Y. pseudotuberculosis compared to uninfected mice." (PMID 26296209, 2015). "We also proved that expression of three inflammatory cytokines, IL6, IL-8 and TNF-α in A549 cells augmented clearly during infection by A. fumigatus." (PMID 26273834, 2015). "D39 infection of TNF-α pre-stimulated PMC abrogated the production of both cytokines in a MOI-dependent manner." (PMID 26566142, 2015).
infection (continued). "Here, we confirmed the level of TNF-α was significantly increased by PR8 infection, which was decreased in the lungs following coadministration of 60% MeOH fraction (fraction 4) of ivy extract containing HSF and oseltamivir." (PMID 26098681, 2015). "Early response cytokines [e.g., tumor necrosis factor and interleukin (IL)-1β] peak within the first hours after infection; circulatory levels then revert to near baseline in 3–4 h." (PMID 25904867, 2015). "The expression level of some proinflammatory molecules (e.g., CCR5, CXCR4, IL1A, IL1R1, IL8, and TNF) peaked on day 3 or 6 following infection." (PMID 25719526, 2015). "The inflammatory cytokine TNF-α promotes local and systemic inflammation while enhancing neutrophil recruitment to the site of infection." (PMID 26042121, 2015). "We determined the relative fold induction of TNF in hDCs following infection with FV1 lpg1− and FV1 lpg2− mutants." (PMID 26630499, 2015). "TNFR1 recognizes cytokines, mainly TNF-α, which is released from leukocytes in order to recruit inflammatory cells to the site of injury and infection." (PMID 25674081, 2015). "TNF and IL-1 are considered to be two key early proinflammatory response cytokines induced following infection." (PMID 25948816, 2015). "Animals treated with 200 mg/kg bw of ALE and ASE produced significant levels of INF-γ, TNF-α, and IL-2 with respect to infection control (P < 0.05)." (PMID 25884649, 2015). "First, TNF-α production is observed as early as 24 hours post-infection, whereas the exosome released from BCG-infected J774 macrophages is primarily detected between 48 and 72 hours post-infection." (PMID 25782003, 2015). "Levels of IL-6 and TNF-α peaked at 48 hours post-infection, while they were significantly decreased by day 4 post-challenge." (PMID 26114641, 2015). "NF-κB signaling is activated through canonical and non-canonical pathways, and the activation of the canonical pathway is mainly triggered by infection and cytokine stimuli such as lipopolysaccharide (LPS), tumor necrosis factor-α (TNFα) and interleukin-1β." (PMID 26269411, 2015). "The infection was characterized by a significant up-regulation of TNF-α gene expression, while expressions of IFN-α2, IFN-β1, IFN-γ and IL-6 remained unchanged compared to mock-infected controls." (PMID 26274828, 2015). "While TNF has a highly deleterious effect in inflammatory joint diseases, it plays a vital role in the body's defenses against infection." (PMID 26097196, 2015). "Our data showed an increase in the percentage of TNF-alpha+ monocytes after the infection with Y strain and Col cl1.7." (PMID 26147698, 2015). "It has been previously demonstrated that IL-10 inhibits accumulation and activation of M1-type myeloid cells, in particular, TIP-DCs (CD11b+Ly6C+CD11c+TNF and iNOS producing DCs) in the liver during infection with African trypanosomes." (PMID 26222157, 2015). "The role of TNF and IL-12 in VL has been described in the literature, both in experimental infection of mice as in canine infection." (PMID 25875101, 2015). "Due to TNF-α’s ability to increase SMC proliferation, R7020 had the greatest effect on SMC number in TNF-α treated cultures where at the higher infection doses it negated the effect of TNF-α." (PMID 26132411, 2015). "This evidence points to the necessity of a TLR4/CD14/MD2 complex that is activated upon detection of Gram-positive bacteria, which is now known to be responsible for rapid TNFα cytokine induction during infection." (PMID 25674081, 2015). "As expected, gene ontology analysis revealed that more than 80% of the genes induced in erythroblasts treated with TNF-α are involved in innate and adaptive immune responses to infection (p<10-15)." (PMID 25781011, 2015). "Analysis of the cytokine and chemokine responses in the lung showed that D39, but not D39Δcps pneumococci despite higher bacterial numbers, triggered the production of TNF-α, IL-6 and KC in the lung 6 hours after infection." (PMID 25700108, 2015).
infection (continued). "Similar to vaginal tissues, uterine samples collected 35 days post-infection with C. trachomatis had increased expression of Il10 and TNF." (PMID 26779389, 2015). "Significantly higher amounts of IFN-γ, IL-12p40, and TNF-α were detected in the plasma of IL-27R-/- mice infected with T. congolense, compared to infected wild-type mice, on day 7 and 10 after infection (p<0.01)." (PMID 26222157, 2015). "In the experiments with cells from healthy Australian blood donors which were controlled for exposure to cigarette smoke and infection, females generally had higher TNF-α responses than males." (PMID 26284064, 2015). "To examine the role of the proinflammatory property of CP in the increased murine mortality, we administered antibodies against IFN-γ, IL-1β, or TNF-α at 2 h post infection and compared the murine mortality." (PMID 26147796, 2015). "The soluble TNF-α was initially detectable at 48 hours post-infection and its level further increased at 72 hours." (PMID 26023919, 2015). "HCV infection induced the expression of TNF-α at two hours post-infection and the simultaneous knockdown of both TLR7 and TLR8 (TLR7/8) impaired this induction." (PMID 26023919, 2015). "During infection and inflammation, macrophages become active in response to a range of stimuli including damaged cells, pathogens and inflammatory cytokines such as TNF-α." (PMID 25699985, 2015). "Convergence in TNF-α count occurred at approximately 14 days after infection, earlier than convergence in HMGB-1 count in innate immunity." (PMID 26446682, 2015). "These researchers found that the cholera toxin down regulated the synthesis of TNF-α thereby inhibiting the innate immunity at the earliest steps of infection." (PMID 26066787, 2015). "TP3 treatment caused a decrease in TNF-α, IL-6, and CXCL5 at the site of infection on days 1, 3, and 5; on the other hand, MRSA infection induced TNF-α and IL-6." (PMID 25992774, 2015). "The cytokine profile (IL-10, IL-6, TNF-α) elicited upon infection with N. gonorrhoeae correlates well with the M2b-MФ phenotype." (PMID 26125939, 2015). "Differences in virus loads and ability to induce cytopathic effect, inhibition of protein synthesis, apoptosis, and induction of IFNa, Mx1, PKR or TNFα gene expression at different times post infection were examined." (PMID 26263557, 2015). "We evaluated the signaling pathways during the infection by measuring the expression of NF-κB (p65), TNF-α, IL-10 and STAT3 by Western blot analysis of hind paw supernatant of each group." (PMID 25973801, 2015). "LTA treatment of THP-1 cells resulted in TNF induction similar to infection with S. pyogenes suggesting that S. pyogenes was recognized through TLR2." (PMID 25756897, 2015). "The expression of IE1–72, TLR2, TLR4, NF-κB and TNF-α mRNA was quantified at different time points prior to and following infection." (PMID 25435993, 2015). "Here, the blunted AM-dependent TNF-α response toward Gram-positive bacterial ligands in SPC-HAxTCR-HA airways suggests a functional impairment of these cells during infection with airborne pathogens." (PMID 26319657, 2015). "M-HA-treated macrophages produce higher TNF-α values at 24 hours post-infection than untreated cells." (PMID 25782003, 2015). "Patients with acquired (i.e., HIV) or pharmaceutical (i.e., steroids, TNF blockers) induced immunosuppression are the most likely to succumb to infection with Ralstonia species." (PMID 25648998, 2015). "By contrast, DRSA infection had little effect on pulmonary expression of TNF-α and IL-1β in SW-EXE mice, although the baseline levels of the two cytokines were already higher than in No-EX mice." (PMID 26542343, 2015). "As IFNγ and TNFα levels increase during clearance of infection, the concomitant increase in IL-4 and IL-6 protects mitochondrial function." (PMID 26481427, 2015). "Infection of BMDMs with MtbΔsigH results in both higher TNF-α expression and greater apoptosis relative to Mtb22." (PMID 26460802, 2015).
infection (continued). "In this study, we documented significantly increased pro-inflammatory cytokines including TNF-α, IL-17, IL-6 and IL-1β in serum at 6 wks post-infection, at which time mating occurred." (PMID 26322971, 2015). "Knockdown of TNF-α expression can enhance HCoV-229E replication, whereas TNF-α pretreatment can decrease the susceptibility of infection in G6PD-knockdown A549 cells." (PMID 26694452, 2015). "Serum levels of the pro-inflammatory cytokines IL-1ß, IL-6, IL-12, and TNF-α and the anti-inflammatory IL-10 appeared similar in anesthetized and Intralipid control animals during the first 48 hours post-infection." (PMID 26381144, 2015). "Despite low levels of TNF-α, IL-6 and KC in the lung early after infection, D39Δcps induced profound lung inflammation like D39, as determined by semi-quantitative pathology scores of lung tissue slides and by measuring neutrophil influx." (PMID 25700108, 2015). "In these studies, six-day M-CSF matured human monocyte derived macrophages (hMDMs) were treated for 24 hours prior to infection with TNFα and/or IFNγ." (PMID 26562011, 2015). "Both infection and TNFα, individually and combined with IFNγ, decreased complex I and IV enzyme levels and mitochondrial function." (PMID 26481427, 2015). "We observed enhanced brain inflammation in all three strains until 2 weeks post-infection, after which inflammation was sustained in TNFf/f and NsTNF−/− mice but significantly decreased (p < 0.05) in TNF−/− mice." (PMID 26112704, 2015). "In the later phase of an infection, the TNF-α blocker contributes to limiting the extent of cell and/or tissue damage by inducing apoptosis and maintaining granuloma formation, which are important mechanisms in T. whipplei infections." (PMID 26215452, 2015). "Later in infection (6 days p.i.), systemic inflammation was dampened in eugenol-treated mice, which showed reduced TNF-α and MCP-1 levels in the spleen." (PMID 25787310, 2015). "At 12 h after infection, the kinetics of TNF-α production in the peritoneum had reversed: while low amounts of TNF-α were found in mice infected with ΔbgsA, mice infected with the wild-type strain or ΔbgsB displayed elevated levels of this cytokine." (PMID 26172831, 2015). "Levels of cytokines that showed large differences between EP and S. mitis (IL-1α, IL-6, KC, M-CSF and TNFα) were assayed in chamber fluid collected at 24 and 168 h after infection with the individual species." (PMID 26171605, 2015). "HOIL-1 KO mice chronically infected with M. tuberculosis also exhibited increased expression of both IL-6 and TNFα in serum at 70 days post-infection." (PMID 25599590, 2015). "These factors are likely the reasons why HCV was also able to induce TNF-α in the later phase of infection." (PMID 26023919, 2015). "Infection with Salmonella stimulates endogenous production of TNF-α and other toxic mediators in the host." (PMID 26068006, 2015). "Piglets treated with LPS and infected with STM14028 showed a significant increase in body temperature and the production of IL-1beta and TNF-alpha in the blood at 4 h post infection." (PMID 26441914, 2015). "Consistent with early observations for the necessity of focusing on the immunomodulatory role of cytokines at the site of infection, Edwards added TNFα for 4 hours pre-exposure to S. aureus." (PMID 26690226, 2015). "The inflammatory markers IL-6, IL-1α and IL1-β were expressed at similar levels in both infections at early times, while TNFα was preferentially present in S. mitis infections." (PMID 26171605, 2015). "Using an in vivo-like in vitro mucosal surface, we identified that infection per se, as well as TNFα, individually and more severely in combination with IFNγ, caused the same effects as seen in vivo." (PMID 26481427, 2015). "We demonstrated that FV1 lpg1− induces significantly less TNF mRNA compared to WT or FV1 lpg1−/+LPG1 add back infections, similar to the pattern of IL12B expression." (PMID 26630499, 2015).
infection (continued). "In a mixed-strain Mtb infection of macrophages, TNF-α production was similar to that induced by infection with perM::tn alone at the same total multiplicity of infection (MOI)." (PMID 25658098, 2015). "A production of proinflammatory cytokines and chemokines including tumor necrosis factor-alpha (TNF-α), IL-6, and IL-8 normally triggers beneficial host innate immune responses to limit the infection and the consequent tissue damage." (PMID 26635427, 2015). "In TNF-α treated cells only the two highest infection levels increased the number of dead cells at 72 h." (PMID 26132411, 2015). "Viral and bacterial infection or stimulation by cytokines such as Interleukin-1, Tumor Necrosis Factor-α, and Transforming Growth Factor-β1 induce interleukin-11 expression in mouse dendritic cells, macrophages, and other tissues." (PMID 25775398, 2015). "TNF cellular responses can eradicate infectious agents, but can also lead to local tissue injury at sites of infection and harmful systemic effects." (PMID 25875101, 2015). "In order to evaluate the role of NKT cells in the present model, we performed cytokine staining (IFNγ, TNFα and IL-4) three days post infection." (PMID 26296209, 2015). "On the other hand, we observed a positive correlation between the expression of TNF-alpha and granzyme A only after infection with Y strain." (PMID 26147698, 2015). "In late 2012, we reported that some genotypes in TNF and LTA are associated with susceptibility to infection with the influenza A (H1N1) pdm09 virus." (PMID 26657940, 2015). "Ciaramella and co-workers also found that infection of human monocytes with MTB induced caspase-1-mediated apoptosis as well as TNFα and IL-1β production." (PMID 25887904, 2015). "This is further supported by the observation that in the WT mice, the mitochondrial respiratory chain remained impaired even at day 19 post infection, when the pathogen burden had subsided, but the expression of TNFα and IFNγ remained elevated." (PMID 26481427, 2015). "Combining treatments of TNFα and IFNγ, in analogy with the in vivo cytokine expression during day 14 and 19 post infection, further decreased complex I and IV activity (−58% and −52%, P < 0.001)." (PMID 26481427, 2015). "Pretreatment of the A549 cells with siRNA against TNF-α significantly reduced HCoV-229E-induced TNF-α expression throughout the course of infection." (PMID 26694452, 2015). "In contrast, infection of L6 myoblasts with Ad-PIMT enhanced TNF-α mediated inhibition of insulin stimulated IRS1Tyr608 and AktSer473 phosphorylation." (PMID 26468734, 2015). "In WT mice, when the concentrations of IFNγ and TNFα increase during clearance of infection, the concurrent induction of IL-4 and IL-6 thus appears to protect the mitochondrial function of the colonic epithelium from further damage." (PMID 26481427, 2015). "As expected, we observed a 2260- and 80-fold induction of IL-6 in the lungs and spleen, respectively, as well as a 21-fold induction of TNF in the lungs of the host at 24 hours post-infection." (PMID 26250699, 2015). "According to previous studies, an appropriate amounts of cytokines, such as IL-1β, IL-6 and TNF-α, is beneficial in response to infection, but overstimulation of the immune system can have detrimental effects." (PMID 26635958, 2015). "As TNF-α plays a central role in the initial host response to infection, this higher response to the chronic strain is unexpected." (PMID 26252386, 2015). "Levels of IL-1ß, IL-6, and TNF-α increased by 72 hours post-infection in drug treated animals, a time point at which bacterial burdens were just beginning to become significantly different than those of controls." (PMID 26381144, 2015). "Acute pain crises in SCD are usually accompanied with infection and/or inflammation, with IL 1-β and TNF-α released." (PMID 25330517, 2014).